ADAM15 (ADAM metallopeptidase domain 15)
Diseases named in the same sentence as ADAM15 in open-access papers (continued):
Sharing a sentence is not in itself a finding about the gene and the disease.
tumor (34 papers, 2005 to 2026). "Elevated ADAM8, ADAM9, ADAM12 and ADAM17 levels were observed in CRC tissues and correlated with more advanced tumor stage, while increased serum ADAM15 concentrations associated with the presence distant metastases." (PMID 41976350, 2026). "Although the percentage of elevated ADAM15 concentration was lower than for classical tumor markers such as CEA and CRP, its diagnostic value notably increased when used in combination." (PMID 40725774, 2025). "The diagnostic sensitivity of ADAM15 (38%) was lower than for the classical tumor markers (CA 19-9—52%, CEA—58%) and CRP (65%)." (PMID 40725774, 2025). "In our present study, the association between serum ADAM15 levels and the tumor stage of CRC according to the TNM classification, as well as clinicopathological characteristics of CRC, was investigated." (PMID 40725774, 2025). "ADAM-15 has been linked to a number of different cancerous diseases as well as to the modulation of epithelial cell-tumor cell interactions." (PMID 37446087, 2023). "The reduction of tumor growth and metastasis by loss of ADAM15 has also been reported by our laboratory and others using different xenograft tumor models." (PMID 26930657, 2016). "According to these data, differential ADAM15 variants expression determines tumor aggressiveness and clinical outcome by different interactions with intracellular pathways; especially ADAM15B due to owning broadest repertoire of interplaying partners is correlated with tumor malignancy." (PMID 38317965, 2024). "However, the level of gene expression in tumor cells was negatively associated with tumor purity, the correlation analysis between ADAM15 expression and immune cell markers was adjusted by tumor purity." (PMID 34426560, 2021). "The area under the ROC curve (AUC) for ADAM15 (0.5070, p > 0.05) was lower than for the classical tumor markers (CA19-9—0.5617, p > 0.05; CEA—0.7519, p < 0.001) and the marker of inflammation (CRP—0.8220, p < 0.001) in the diagnosis of CRC." (PMID 40725774, 2025). "Based on the diagnostic criteria, serum ADAM15 seems to be a candidate marker for CRC diagnosis, especially in combined use with a classic tumor marker—CEA." (PMID 40725774, 2025). "We aimed to assess the association between serum levels of ADAM15 and the clinicopathological characteristics of CRC, as well as its potential significance as a candidate tumor marker in the diagnosis of CRC patients." (PMID 40725774, 2025). "The combined analysis of ADAM15 and CEA increased the diagnostic sensitivity up to 67% and was higher than the assessment of classical tumor markers in combination (CEA + CA19-9 = 62%)." (PMID 40725774, 2025). "ADAM12, when interacting with its integrin substrates, exhibited an inverse relationship with tumor growth, whereas ADAM15’s interaction with integrin beta 3 (ITGB3) was positively correlated with tumor growth." (PMID 39519201, 2024). "This study suggests that ADAM15 exosomes derived from macrophages participate in tumor inhibition in vivo." (PMID 37981718, 2023). "Then, tumours formed from the ADAM15-overexpressing cells treated with defactinib (VS-6063) were much smaller in size than those formed from the control cells." (PMID 35597804, 2022). "In our study, we also demonstrated that ADAM15 regulated the migration and invasion of tumours by affecting MMP9." (PMID 35597804, 2022). "Tumours formed from the cells with ADAM15 overexpression were much larger in size than those formed from the control cells." (PMID 35597804, 2022). "The tissues resected from the xenograft tumours were analysed to verify ADAM15 expression, and qRT-PCR showed that the ADAM15 mRNA levels in the ADAM15 overexpression group were increased compared with those in the control group." (PMID 35597804, 2022). "On the other hand, overexpression of ADAM15 promoted tumour growth, as evidenced by increased tumour volume and tumour weight." (PMID 35597804, 2022).
tumor (continued). "Collectively, this gave us reason to believe that ADAM15 increased the proliferation, migration and invasion capacities, at leastin part by modulating tumor immune infiltration." (PMID 34426560, 2021). "Exosomes highly expressing ADAM15 have been found to show an enhanced binding affinity for integrin αvβ3, which is overexpressed on many tumours." (PMID 33477629, 2021). "In vivo studies also showed significant tumour suppression in a xenografted-nude mouse model by ADAM15-rich exosomes." (PMID 33477629, 2021). "At the same time, our results demonstrated that ADAM15 expression was closely related to tumor immune infiltration via bioinformatics analysis, but in vitro and in vivo experiments were needed to dissect the role of ADAM15 in tumor immunity." (PMID 34426560, 2021). "In a related study, HCC xenografts in zebrafish embryos were produced using Bel-7402 hepatoma cell line; and the effect of ADAM15 recombinant human disintegrin domain (rhddADAM15) was analyzed on tumor growth and metastasis." (PMID 29371671, 2018). "Tumor cell-derived exosomes, enriched in ADAM15, display a high binding affinity for integrin αvβ3 and suppress cell adhesion, migration and growth." (PMID 29404342, 2018). "Exosomes derived from macrophages have also been shown to express ADAM15 and demonstrate described tumor inhibitory effects." (PMID 29404342, 2018). "This is supported by our in vitro observations and early in vivo results by which the reduction of ADAM15 expression or inhibition of its catalytic activity, reduces cellular motility and invasiveness and inhibits tumor growth in animal models." (PMID 26930657, 2016). "To investigate the effect of ADAM15 ablation in tumor development, we employed our UM-UC-6 model using the same silencing shRNA sequences and procedures described in the methods section." (PMID 26930657, 2016). "ADAM15 is emerging as a potential regulator of the tumor microenvironment and its promise for therapeutic targeting is rising." (PMID 26930657, 2016). "The knockdown of ADAM15 decreased the UM-UC-6 tumor growth by 44.5% (ctlA15UC6 49.9±9.81mg, shA15UC6 24.7±3.60mg)." (PMID 26930657, 2016). "In the tumor group, statistic ally-significant high mRNA expression levels of ADAM15 and CDC7 were consistently detected by using the qRT-PCR (p<0.001 and p<0.001, respectively), thus showing excellent agreement with the microarray data." (PMID 25475780, 2015). "The significant reduction of TIMP3 (an endogenous inhibitor of MMPs) and increase of ADAM15 transcripts, shared by both cell lines, emphasize an imbalance of MMPs functions in tumor cells overexpressing CD157." (PMID 22916288, 2012). "ADAM15 is expressed in blood vessels and endocardium, and although ADAM15 mice are viable studies using retinopathy and tumor angiogenesis models demonstrate an inducible vascular phenotype (failure of remodeling of the primary capillary plexus)." (PMID 19156209, 2009). "In addition, the measurement of serum ADAM15 concentrations, especially in combination with well-established tumor marker-CEA improved the diagnosis of patients with this malignancy." (PMID 41976350, 2026). "Serum concentrations of ADAM15 and classical tumor markers (CEA and CA 19-9), as well as the marker of inflammation CRP, were higher in CRC patients in comparison to healthy controls; however, these differences were significant only for serum CEA (p < 0.001) and CRP (p < 0.001) levels." (PMID 40725774, 2025). "However, our study as the first to evaluate the significance of serum ADAM15 as a candidate tumor marker in the diagnosis and progression of CRC." (PMID 40725774, 2025). "However, to the best of our knowledge, the present study is the first to demonstrate serum concentrations of ADAM15 in relation to well-established tumor markers for CRC, such as CEA and Ca 19-9, as well as a marker of inflammation—C-reactive protein (CRP)." (PMID 40725774, 2025).
tumor (continued). "In addition, exosomal a disintegrin and metalloproteinase 15 (ADAM15) from TAMs can slow tumor growth and improve survival when co-injected with tumor cells into nude mice." (PMID 40756366, 2025). "This soluble form of ADAM15 can be detected in serum and may reflect pathological processes within the tumor microenvironment, including tumor–host interactions." (PMID 40725774, 2025). "Measurement of serum ADAM15, especially in combination with classical tumor markers (CEA) and inflammation markers (CRP), may improve the diagnosis of patients with CRC." (PMID 40725774, 2025). "Therefore, the goal of our study was to assess the usefulness of serum ADAM15 as a potential novel tumor marker of CRC in comparison to well-established tumor markers such as CEA and CA 19-9, as well as CRP." (PMID 40725774, 2025). "Besides, analysis of immune infiltration indicated that ADAM15 expression was related to tumor infiltrating lymphocytes based on the TIMER, TISIDB and GEPIA databases." (PMID 34426560, 2021). "On the one hand, ADAM15 promoted cell adhesion so as to decrease tumor cell migration." (PMID 33062410, 2020). "Aberrant metalloproteinase function of ADAM15 may contribute to tumor progression through the release of growth factors or disruption of cell adhesion." (PMID 26930657, 2016). "ADAM15 may down-regulate adhesion of tumor cells to the extracellular matrix, reduce cell-cell adhesion, and promote metastasis through the activity of its disintegrin and metalloproteinase domains." (PMID 25693204, 2015). "Given its diverse functions, ADAM15 may represent a pivotal regulatory component of tumor progression and an important target for therapeutic intervention." (PMID 25693204, 2015). "Therefore, elevated levels of soluble ADAM15 in the serum may not only indicate tumor presence but also dynamic changes related to metastatic progression." (PMID 40725774, 2025). "In our investigation, we reported that serum ADAM15 concentrations were higher in CRC patients compared to healthy controls, similar to the classical tumor markers and CRP; however, significant differences were only observed for CEA and CRP." (PMID 40725774, 2025). "Metalloproteinase ADAM15 and MMP2 were expressed in tumor-like cells and tumor spheres to some extent but notably absent in normal organoids and organoid slices." (PMID 40917877, 2025). "We found the increased expression of PFKP, TPX2, UBE2S, ST6GALNAC4, ADAM15, G6PD, and KPNA2, but decreased expression of GOT2 in tumor samples compared to normal samples." (PMID 40307857, 2025). "A disintegrin and metalloproteinase-15 (ADAM15), a member of the ADAM protein family, inhibits tumor progression." (PMID 37981718, 2023). "High expression of ADAM-15 and ADAM-12 were found in PC tissues and sera/urine of patients affected by PC with advanced pathological tumor stages with metastasis, respectively." (PMID 35011576, 2021). "The concurrent high expression of disintegrin metalloproteinase 15 (ADAM15) further enhances integrin-dependent tumor growth and metastasis in NSCLC, as ADAM15 is the only member of the metalloproteinase family located on the cell membrane that contains an RGD fragment in the disintegrin domain." (PMID 40649983, 2025). "The dual-luciferase reporter assay confirmed that miR-204-5p has binding sites with ADAM15, and miR-204-5p can inhibit ADAM15-induced proliferation of NSCLC, which further confirms the tumour promoting function of ADAM15 and provides more clues to the regulation network of ADAM15." (PMID 35597804, 2022). "ADAM15 expression was significantly increased in tumor tissue (p<0.001) by an average of 2.7-fold compared with normal tissue." (PMID 25475780, 2015). "Two of them, ADAM15 and MMP11, were known to play important roles in tumor invasion." (PMID 23211491, 2012). "Moreover, it was indicated that some of the tumor patients (26%) who were negative for CRP presented positive concentrations of ADAM15." (PMID 40725774, 2025).
tumor (continued). "Thus, the aim of our study was to focus on the measurement of ADAM15 concentrations in the serum of CRC patients without parallel analysis in tumor tissue, as well as the mRNA or protein level." (PMID 40725774, 2025). "However, we reported that some of the tumor patients (26%) who were negative for CRP presented positive concentrations of ADAM15." (PMID 40725774, 2025). "Among 9 ADAMs, only ADAM15 correlated with neither tumor purity nor any immune infiltrate." (PMID 33062410, 2020). "Importantly, we reported for the first time an up-regulation of ADAM15, ADAM21, ADAM22, ADAM23 in tumors compared with adjacent non tumor tissues, however only ADAM15 is indicative of worse prognosis (0.007)." (PMID 33805340, 2021).
infection (3 papers, 2011 to 2020). The state of being infected such as from the introduction of a foreign agent such as serum, vaccine, antigenic substance or organism. "So far, the contribution of ADAM15 has been only investigated in models of sterile infection." (PMID 33392273, 2020). "Further, in vitro studies revealed a more complex action of ADAM15 in inflammation and infection." (PMID 33392273, 2020). "ADAM10 and ADAM17 together with ADAM8 and ADAM9 seem to be the most relevant ADAM proteases in infection; however, some studies point toward an additional influence of ADAM12, ADAM15, and ADAM33." (PMID 33392273, 2020). "We found that the levels of ADAM17, not ADAM15 or ADAM19, increased significantly upon infection." (PMID 30687645, 2018). "Interestingly, we found that while the metalloprotease domain of ADAM10 is not required for HIV-1 replication, ADAM15 and γ-secretase (which proteolytically release the extracellular and intracellular domains of ADAM10 from the plasma membrane, respectively) do support productive infection." (PMID 21569301, 2011).
hematologic diseases (1 paper, 2025). "Expression of ADAM15 in cells (e.g., U937 or Jurkat) derived from hematologic diseases has been reported, while biological functions have not been investigated in depth." (PMID 41340056, 2025).
ADAM15 also shares sentences with these, for which no sentence is quoted: prostate tumor (2 papers); retinopathy (2); acute lymphoblastic leukemia (1); allergic disease (1); allergic rhinitis (1); Angina (1); astrocytic tumor (1); atrial fibrillation (1); brain tumor (1); breast tumor (1); cardiac disease (1); diabetes (1); gastritis (1); glioblastoma (1); Hyperglycemia (1); inflammation (1); invasive breast carcinoma (1); metastatic cancer (1); narcolepsy (1); ovarian carcinoma (1); Parkinson disease (1); renal cell carcinoma (1); retinopathy of prematurity (1); type 1 diabetes (1).